CNOT3 (CCR4-NOT transcription complex subunit 3)
Description:
Component of the CCR4-NOT complex which is one of the major cellular mRNA deadenylases and is linked to various cellular processes including bulk mRNA degradation, miRNA-mediated repression, translational repression during translational initiation and general transcription regulation. Additional complex functions may be a consequence of its influence on mRNA expression. May be involved in metabolic regulation; may be involved in recruitment of the CCR4-NOT complex to deadenylation target mRNAs involved in energy metabolism. Involved in mitotic progression and regulation of the spindle assembly checkpoint by regulating the stability of MAD1L1 mRNA. Can repress transcription and may link the CCR4-NOT complex to transcriptional regulation; the repressive function may involve histone deacetylases. Involved in the maintenance of embryonic stem (ES) cell identity.
Synonyms: KIAA0691; LENG2; NOT3; NOT3H; IDDSADF
Tractability: Small molecule: a structure with a bound ligand is known. PROTAC: ubiquitination databases record sites on it; its protein half-life has been measured.
Gene: Protein-coding gene on chromosome 19 (54,137,710 to 54,155,708, forward strand). Ensembl gene ENSG00000088038.
Subcellular location: Cytoplasm; Nucleus; Cytoplasm, P-body
Subcellular location (Human Protein Atlas): Cytosol
Pathways (Reactome):
Developmental Biology: M-decay: degradation of maternal mRNAs by maternally stored factors
Metabolism of RNA: Deadenylation of mRNA
Gene Ontology:
Molecular function: protein binding
Biological process: regulation of stem cell population maintenance; determination of left/right symmetry; mRNA catabolic process; nuclear-transcribed mRNA poly(A) tail shortening; positive regulation of cold-induced thermogenesis; regulation of DNA-templated transcription; trophectodermal cell differentiation
Cellular component: CCR4-NOT complex; CCR4-NOT core complex; cytosol; P-body; cytoplasm; nucleus
Genetic constraint (gnomAD): Loss-of-function variants: 1 observed, 83.03 expected, observed/expected ratio (o/e) 0.012, 90% interval 0.003 to 0.057. The synonymous counts are far from expectation, so gnomAD's model fits this gene poorly and the ratio says little. Missense variants: 624 observed, 941.83 expected, observed/expected ratio (o/e) 0.66, 90% interval 0.62 to 0.71. Synonymous variants: 459 observed, 383.78 expected, observed/expected ratio (o/e) 1.2, 90% interval 1.11 to 1.29.
Gene-disease validity (ClinGen):
ClinGen rates the evidence that CNOT3 causes each of these diseases.
complex neurodevelopmental disorder (autosomal dominant): Definitive. A disorder that involves more than one phenotype associated with the central nervous system, including but not limited to intellectual disability, autism, and seizures (epilepsy).
Cancer hallmarks: escaping programmed cell death (promotes); suppression of growth (promotes)
Homologues: Orthologues: chimpanzee CNOT3 (100% identical), dog CNOT3 (97% identical), rabbit CNOT3 (96% identical), guinea pig CNOT3 (95% identical), rat Cnot3 (95% identical), mouse Cnot3 (95% identical), pig CNOT3 (94% identical), macaque CNOT3 (91% identical), tropical clawed frog cnot3 (79% identical), zebrafish cnot3a (70% identical), zebrafish cnot3b (69% identical), Drosophila melanogaster Not3 (44% identical), and 1 more. Paralogues in human: CNOT2 (17% identical).
Diseases named in the same sentence as CNOT3 in open-access papers:
CNOT3 is named in the same sentence as 53 diseases in open-access papers, as found by Europe PMC text mining. Sharing a sentence is not in itself a finding about the gene and the disease. The quoted sentences say what the papers report.
acute lymphoblastic leukemia (5 papers, 2017 to 2022). Leukemia with an acute onset, characterized by the presence of lymphoblasts in the bone marrow and the peripheral blood. "We recently identified CNOT3 loss-of-function mutations in patients with T-cell acute lymphoblastic leukemia (T-ALL)." (PMID 30144809, 2018). "In this regard, it is interesting that frequent mutations in RPL5 and RPL10 or in CNOT3 have been observed to accumulate in adult T-cell acute lymphoblastic leukemia (T-ALL)." (PMID 28588606, 2017). "Exome sequencing revealed mutations in CNOT3 and the ribosomal genes RPL5 and RPL10 in acute lymphoblastic leukemia." (PMID 36147491, 2022). "Moreover, mutations of the CNOT3 gene were discovered in samples of T-cell acute lymphoblastic leukemia (T-ALL) patients, suggesting the tumour suppressor role of CNOT3." (PMID 31572192, 2019). "Indeed, mutations in CNOT3, the ortholog of Not5, or in the RPL5 and RPL10 ribosomal proteins, are associated with adult T-cell acute lymphoblastic leukemia (T-ALL)." (PMID 28588606, 2017).
T-cell acute lymphoblastic leukemia (5 papers, 2017 to 2021). Acute lymphoblastic leukemia of T-cell origin. "Although how CNOT2 and CNOT3 function in the catalytic subunit during the oral cancer process remains unclear, a mutation in CNOT3 is associated with non-small cell lung cancer and T-cell acute lymphoblastic leukemia." (PMID 31724941, 2019).
autism (4 papers, 2021 to 2025). Persistent deficits in social interaction and communication and interaction as well as a markedly restricted repertoire of activity and interest as well as repetitive patterns of behavior. "Of note, CNOT3 is categorized as a “High-confidence, syndromic” autism risk gene in the SFARI autism gene database." (PMID 39913536, 2025). "For example, CNOT3 was associated with IDDSADF (an intellectual developmental disorder with speech delay, autism, and dysmorphic facies), which will cause abnormal facial morphosis." (PMID 33824393, 2021). "Heterozygous loss-of-function variants in CNOT3, encoding a subunit of the CCR4-NOT protein complex, have recently been reported to cause a syndromic condition known as intellectual developmental disorder with speech delay, autism and dysmorphic facies (IDDSADF)." (PMID 34208845, 2021).
leukemia (4 papers, 2015 to 2024). A malignant (clonal) hematologic disorder, involving hematopoietic stem cells and characterized by the presence of primitive or atypical myeloid or lymphoid cells in the bone marrow and the blood. "Given the association of CNOT3 with several translation elongation factors, we examined the functional relevance of these EEFs in leukemia cells." (PMID 38491013, 2024). "Loss of CNOT3 significantly delayed leukemia development and improved survival of recipient animals." (PMID 38491013, 2024). "Furthermore, CNOT3 associates with the protein network largely consisting of ribosomal proteins and translation elongation factors in leukemia cells." (PMID 38491013, 2024). "While the in vitro and in vivo phenotypes are highly agreeable, it remains to be determined whether loss of CNOT3 can lead to any homing defects in both normal and leukemia cells." (PMID 38491013, 2024). "CNOT3 has been proposed to function as a tumor suppressor gene and was found to be mutated at high frequencies in T-cell lymphoblastoid leukemia cells, while in colorectal and non-small cell lung cancers, CNOT3 overexpression was shown to promote proliferation." (PMID 34680937, 2021). "It is intriguing to speculate that these mutations may be involved in development of leukemia by disabling CNOT3-target mRNA recognition." (PMID 26437789, 2015). "We uncovered CNOT3 as a key regulator of translation control in leukemia and nominated CNOT3 as a potential therapeutic target for the treatment of AML." (PMID 38491013, 2024). "Our data suggests that, at least in leukemia cells, CNOT3 plays a significant role in ensuring efficiency of translation process." (PMID 38491013, 2024). "Knockdown of CNOT3 induced differentiation in leukemia cells evidenced by elevated expression of CD11b and CD14 cell surface markers and changes in cellular morphology and increased apoptosis." (PMID 38491013, 2024). "In our study, we observed minimal impact on CNOT1 protein abundance, at least at the early time points when CNOT3 was depleted in leukemia cells and HSPCs." (PMID 38491013, 2024). "Taken together, the data established a critical role for CNOT3 in leukemia development." (PMID 38491013, 2024). "Overall, we propose that CNOT3 functions to boost translation efficiency, hence alleviating the bottlenecks in protein synthesis of growth-promoting proteins essential for the rapidly dividing leukemia cells." (PMID 38491013, 2024). "In leukemia cells, we instead found a dominant association between CNOT3 (and the CCR4-NOT complex) and ribosomal proteins, tRNA synthetases, and translation elongation factors." (PMID 38491013, 2024). "We next want to examine whether CNOT3 is differentially required between leukemia cells vs. normal hematopoietic stem/progenitor cells (HSPCs)." (PMID 38491013, 2024). "In addition, using three patient-derived AML xenotransplantation (PDX) models, we demonstrated that depletion of CNOT3 significantly hindered engraftment and disease progression of leukemia cells in vivo." (PMID 38491013, 2024). "To test whether CNOT3 is required for leukemogenesis, we injected leukemia cells transduced with control (scramble shRNA) and shRNAs (KD-33 and KD-37) against CNOT3 into NSG immunodeficient mice and followed leukemia development in vivo." (PMID 38491013, 2024). "The downregulated effects are in line with the alternations in transcriptomic profiles of CNOT3-depleted cells, suggesting that CNOT3 mediates translation activity to further enforce the expression of the growth-driven genes to promote proliferation and survival of leukemia cells." (PMID 38491013, 2024). "In addition, we found that CNOT3 is differentially required in normal HSPCs vs. leukemia cells." (PMID 38491013, 2024). "On the other hand, we overexpressed CNOT3 in MOLM13, NB4, and THP-1 cells and observed that increased CNOT3 expression significantly augmented the growth of leukemia cells." (PMID 38491013, 2024).
leukemia (continued). "Overall, these data indicated that the NOT box domain is required for CNOT3 function in promoting the growth of leukemia cells." (PMID 38491013, 2024). "The interaction of CNOT3 with the translational machinery is well aligned with the results on CNOT3 structure-function and the link between CNOT3 and AU3 vs. GC3 content of mRNAs, pointing to a dominant role in codon sensing and modulation of translation activity by CNOT3 in leukemia." (PMID 38491013, 2024). "However, CNOT3 depletion did not induce apoptosis in HSPCs, pointing to the differential response when compared to leukemia cells." (PMID 38491013, 2024). "Here the authors uncovered CNOT3, a subunit of the CCR4-NOT complex, as an essential modulator of translation in leukemia." (PMID 38491013, 2024). "Here, we demonstrated that the subunit CNOT3 of the CCR4-NOT complex is required for survival and growth of leukemia cells in vitro and in vivo." (PMID 38491013, 2024).
non-small cell lung carcinoma (4 papers, 2019 to 2024). A group of at least three distinct histological types of lung cancer, including non-small cell squamous cell carcinoma, adenocarcinoma, and large cell carcinoma. "The leading genes contributing towards a higher targeting of RNA degradation among males include CNOT1, CNOT2, CNOT3 and DCP1A, all of which have previously been found to have prognostic significance in various cancers, including non-small cell lung cancer." (PMID 39107837, 2024).
Obesity (4 papers, 2021 to 2025). Accumulation of substantial excess body fat. "In keeping with these findings, mice with reduced CNOT3 expression exhibit increased respiration and are resistant to obesity, consistent with an increase in mitochondrial energy expenditure." (PMID 39571015, 2024). "A study in mice found that Cnot3 haploinsufficiency resulted in higher metabolism, lower serum triglycerides, and obesity resistance in response to a high-fat diet, and preferentially upregulated fat oxidation genes and downregulated lipogenic genes." (PMID 34073619, 2021). "Since heterozygous knockout of Cnot3 decreases body size and confers resistance to high fat diet (HFD)-induced obesity, we anticipate that Cnot4 heterozygous mice are also resistant to obesity." (PMID 40424271, 2025). "Previous reports on gene knockout mice of CCR4-NOT components, such as CNOT3, CNOT6L and CNOT7, have demonstrated that CCR4-NOT complex plays roles in suppressing diet-induced obesity and improving metabolic disorder through degradation of target mRNAs." (PMID 40424271, 2025).
colorectal cancer (3 papers, 2018 to 2025). A primary or metastatic malignant neoplasm that affects the colon or rectum. "It increases the activities of CNOT3 in HCT-116 Colorectal cancer cell line (0.20), CBFB in ME-1 Leukaemia cell (0.13), H3K36me3-marked transcription in Left Ventricle (0.12) and Adipose Nuclei (0.12), and H3K-27me3-marked repression in Astrocyte (0.12)." (PMID 40656995, 2025). "Instead, CNOT3 confers an aggressive behavior in colorectal cancer cells through a self-renewal transcriptional program." (PMID 30144809, 2018). "Cnot3 is necessary for self-renewal of embryonic stem cells and the silencing of it led to replication arrest at the early stage of colorectal cancers." (PMID 29545936, 2018).
heart failure (3 papers, 2017 to 2021). Inability of the heart to pump blood at an adequate rate to meet tissue metabolic requirements. "A more recent study has shown that loss of CNOT1 or CNOT3 results in autophagy and cell death in mouse cardiomyocytes, long QT intervals and heart failure." (PMID 33138308, 2020). "Interestingly, a previous study revealed that heterozygous Cnot3 knockout mice displayed impaired cardiac contractility and increased susceptibility to heart failure, further indicating the multiple roles of Cnot3 in cardiac cell fate decisions." (PMID 28473716, 2017).
adenoma (2 papers, 2019 to 2021). A neoplasm arising from the epithelium. "Remarkably, the CNOT3 E20K and E70K mutations we found in adenoma tissues are the two most common mutations found in numerous cancer types." (PMID 31231471, 2019). "In the COSMIC database, the two most common CNOT3 mutations in cancers are E → K mutations at amino acid positions 20 and 70, which are the CNOT3 mutations we found in our adenoma samples." (PMID 31231471, 2019). "Seven adenomas (19%) harbored somatic CNOT3 mutations, with the K286E mutation found in four of the samples." (PMID 31231471, 2019). "The percentage of CNOT3 mutations (~20%) in FAP adenoma samples that we previously reported and corroborated in this manuscript is higher compared to the TCGA data that contains only sporadic and inherited colon cancer samples." (PMID 31231471, 2019). "Overall, our work supports a mechanism where CTBP1 regulates CNOT3 and that overall CNOT3 perturbation could work in concert with germline APC mutations in advancing adenomas to a more transformed state prior to progression to adenocarcinoma." (PMID 31231471, 2019). "We previously reported that CNOT3 mutations occur in FAP adenoma." (PMID 31231471, 2019). "Next, we determine whether the two CNOT3 mutations identified in FAP adenomas affect wildtype CNOT3 function in vivo by co-injecting each one with cnot3a mo into 1-2 cell stage zebrafish embryos." (PMID 31231471, 2019). "However, our study does create a rationale for studying CNOT3 mutations in the context of adenoma progression to colon carcinoma." (PMID 31231471, 2019). "Since CNOT3 mutations occur more favorably in FAP patients, our observations are very relevant in the context of personalized medicine and justifies the need to further characterize the novel “CNOT3-mutant FAP adenoma” subset in more detail." (PMID 31231471, 2019). "Surprisingly, when the APC gene is excluded, one gene with frequent accumulating genomic alterations CCR4-NOT Transcription Complex Subunit 3 (CNOT3), which was observed in 5 out of 25 sequenced FAP adenomas." (PMID 31231471, 2019).
colon carcinoma (2 papers, 2019 to 2024). "On the other hand, high expression of CNOT3 is associated with higher-grade colon cancer, exhibiting a similar oncogenic function." (PMID 38491013, 2024). "In the colon cancer subset (594 samples), APC and CNOT3 were altered in 66.67% and 1.18% of cancers, respectively." (PMID 31231471, 2019).
hepatocellular carcinoma (2 papers, 2019 to 2023). A malignant tumor that arises from hepatocytes. "Reporter assays using Hepa1-6 cells, a murine hepatoma cell line, showed that Cnot3 regulates amounts of reporter genes in a manner dependent on each 3′UTR." (PMID 30733279, 2019).
Infertility (2 papers, 2023 to 2025). "The infertility and total loss of germ cells in Cnot3-cKO testes suggested a loss of SSCs and thereby a potential role of Cnot3 in SSC maintenance." (PMID 40814964, 2025). "CNOT3 is particularly abundant in undifferentiated spermatogonia, and its deletion in spermatogonia led to germ cell loss and infertility." (PMID 40814964, 2025). "Cnot3 is highly expressed in undifferentiated spermatogonia, and its deletion in spermatogonia resulted in germ cell loss and infertility." (PMID 37873304, 2023). "Therefore, it is conceivable that the reduced ROS level in Cnot3 deletion impairs spermatogonial maintenance, contributing partly to the phenotype of germ cell loss and infertility in vivo." (PMID 40814964, 2025).
acute myeloid leukemia (1 paper, 2024). Acute myeloid leukemia (AML) is a group of neoplasms arising from precursor cells committed to the myeloid cell-line differentiation. "The work pointed to the potential of targeting the posttranscriptional circuitry via CNOT3 as a therapeutic vulnerability in acute myeloid leukemia." (PMID 38491013, 2024). "Elevated CNOT3 expression correlates with unfavorable outcomes in patients with acute myeloid leukemia (AML)." (PMID 38491013, 2024).
adenovirus infection (1 paper, 2018). "The levels of at least 2 other members of the complex (CNOT3 and CNOT7) are also reduced during adenovirus infection, whereas the levels of CNOT4 and CNOT1 remain stable." (PMID 29593045, 2018).
anemia (1 paper, 2019). A reduction in the number of red blood cells, the amount of hemoglobin, and/or the volume of packed red blood cells. "Therefore, loss of Cnot3 resulted in abnormal liver functional maturation concomitant with cell death, anemia and characteristics of damaged liver." (PMID 30733279, 2019). "While 4- and 8-week-old Cnot3−/− livers displayed various abnormalities such as irregular hepatocyte alignment, necrosis, inflammation and anemia, our preliminarily studies detected milder liver pathology and appearance of Cnot3-expressing hepatocytes at later stages (12-16 weeks of age)." (PMID 30733279, 2019). "Mice lacking Cnot3 in liver have reduced body and liver masses, and they display anemia and severe liver damage." (PMID 30733279, 2019).
Arrhythmia (1 paper, 2020). Any cardiac rhythm other than the normal sinus rhythm. "We had previously observed double-beat early afterdepolarization (EAD)-associated arrhythmias in M-mode traces from movies of CNOT3/Not3 knockdown fly hearts, thus an effort was made to record electrophysiological traces." (PMID 32471864, 2020).
autism spectrum disorder (1 paper, 2020). A spectrum of developmental disorders that includes autism, and Asperger syndrome. "Recent SFARI study has identified missense mutations in miRISC proteins AGO1, TNRC6B, and CNOT3 among patients diagnosed with Autism Spectrum Disorders Patients with microdeletions of chromosomal region 1p34.3 encompassing the AGO1 and AGO3 genes also show several neurodevelopmental defects." (PMID 32118035, 2020).
B cell lymphoma (1 paper, 2017). "Upregulation of MHC II genes did not occur after knock-out of CNOT3 in T cells (data not shown) or after knock-down of CNOT2 in Raji B cell lymphoma cells." (PMID 28615693, 2017).